CD80 (CD80 molecule)
Diseases named in the same sentence as CD80 in open-access papers (continued):
Sharing a sentence is not in itself a finding about the gene and the disease.
tumor (continued). "Studies show that CD80 acts as a functional ligand for CTLA-4, particularly in tumour models where CD80-transfected tumours exhibit reduced immunogenicity compared to those with CD86." (PMID 40725864, 2025). "DAC also induces CD80 expression on cancer cells, amplifying tumor-specific cytotoxic T lymphocyte responses." (PMID 41029427, 2025). "For instance, nanovesicles derived from genetically modified tumor cells with CD80 overexpression provided the necessary dual signals to boost antitumor immunity mediated by CD8+ T cells." (PMID 40114728, 2025). "Nevertheless, in models where both modalities of interaction coexist, the net result of blocking the PD-L1/CD80 interaction in vivo is an increased T cell-mediated anti-tumor immunity." (PMID 41425548, 2025). "Of note, a recent study suggests that co-expression of CD80 in exosomes carrying PD-L1 results in inhibition of immunosuppressive and tumor-promotive effects." (PMID 41294803, 2025). "In CCH, CD80 showed a declining expression, which is putatively related to tumor regression, while CD86 showed comparable levels." (PMID 40271486, 2025). "While we would anticipate that CD80 and CD86 would have a positive impact on anti-tumor immunity, we demonstrate that blockade of CD80 and CD86 signaling limits CD4 infiltrates in tumors and prevents the Treg expansion caused by radiation treatment." (PMID 41417245, 2025). "DCs capture tumor-associated antigens and express co-stimulatory molecules, such as CD86 and CD80, forming peptide-MHC complexes that are presented to T lymphocytes to elicit an anti-tumor immune response." (PMID 40303336, 2025). "Tumors hijack these pathways by expressing ligands, such as CD80 and PD-L1, which rewire and deactivate T cells within the tumor microenvironment leading to immune escape." (PMID 40981113, 2025). "Strikingly, untreated A375s yield HMDMs exhibiting a tumor-associated macrophage phenotype characterized by CD40, CD80, and CD206 surface expression while injured A375s yield HMDMs with markers of increased antigen presentation, namely HLADR and CD86." (PMID 40539073, 2025). "Specifically, IL-17 signaling has been shown to regulate the expression of CD70 and CD80 in antigen-presenting cells while promoting TIGIT-mediated suppression in the tumor microenvironment, depending on cytokine context." (PMID 40565233, 2025). "Whereas in the Comb group, tumor size was positively correlated with CD206+CD80− M2 macrophages, suggesting larger tumors have greater numbers of M2 macrophages." (PMID 40400098, 2025). "There was a slight alteration in CD80 and H-2Kb expression after lamin knockdown, suggesting their minimal contribution to the anti-tumor effect of lamin knockdown." (PMID 40708945, 2025). "Tregs, tumor-associated macrophages, and myeloid-derived suppressor cells inhibit T-cell activity via PD-1/PD-L1 and CTLA-4/CD80/86 pathways, while OSCC cells release VEGF, TGFβ, IL-6, and IL-10 to suppress immunity." (PMID 40924302, 2025). "The most significant influence was observed for M1-like macrophages, for which the tumor cell medium alone strongly induced the expression of the costimulatory molecules CD80 and CD86, as well as MHC II." (PMID 40724825, 2025). "We further showed an enrichment of CD4+ and CD8+ T cells as well as total and CD80+ macrophages, confirming immune cell infiltration in tumours treated with IL‐12 minicircle‐loaded RBCEVs." (PMID 39193804, 2025). "In a recent study, a comparable CRISPRa technique was utilized to simultaneously activate multiple endogenous genes such as Cd70, Cd80, Cd86, Ifnα4, Ifnβ1, and Ifnγ, triggering anti-tumor adaptive immune clearance of tumor cells in a mouse model." (PMID 41283440, 2025). "The expression of PD-L1 on TIL can lead to their suppression by binding to CD80 (B7-1) on other cells, like tumor cells or other infiltrating immune cells (in trans)." (PMID 41463212, 2025).
tumor (continued). "Tregs can inhibit tumor-specific lymphocytes through the secretion of PD-L1, which attaches itself to receptors on T cells like PD-1 (B71) or CD80." (PMID 40091960, 2025). "As we will discuss later, DCs, being both strong expressers of PD-L1 and the main source of CD80, are increasingly recognized as key regulators of anti-tumor immunity in response to PD-1/PD-L1 blockade." (PMID 41425548, 2025). "PD-1, PD-L1, and CD80 are negative regulators of anti-tumor immunity that suppress the anti-tumor function of T-cells." (PMID 39866232, 2025). "Our results show that miR-16 directly targets the 3′UTRs of CD40 and CD80, two important modulators of the tumor immune microenvironment." (PMID 40647495, 2025). "Further, PD-L1 interacts with CD80 on the surface of activated CD8+ T-cells to suppress its anti-tumor activity." (PMID 39866232, 2025). "M1 macrophages, known for their pro-inflammatory and anti-tumor functions, typically express markers such as CD80, CD86, and IL12." (PMID 41019045, 2025). "Immune checkpoint blockade in melanoma models revealed that tumor-infiltrating lymphocyte efficacy strongly correlated with moDCs populations expressing elevated CD80, CD86, and MHC-II." (PMID 40924040, 2025). "M1 macrophages (CD86+CD80+) are critical for suppressing tumor growth, while M2 macrophages (CD206+CD163+) display protumor properties." (PMID 39774471, 2025). "We propose to investigate the effectiveness of anti-CTLA-4 mAbs in combination with anti-CD80 mAbs compared to administration of anti-CTLA-4 mAbs alone using the murine tumour model." (PMID 40725864, 2025). "Blocking TREM2 signaling promotes cross-presentation of tumor antigens, boosts CD80/CD86 levels, and synergizes with anti–PD-1 therapy to control tumor growth." (PMID 40821795, 2025). "Tumor cells expressing CD80/86 can induce the translocation of CTLA4 from the cytoplasm to the cell surface in tumor-infiltrating lymphocytes, resulting in the suppression of T lymphocyte activity." (PMID 39941803, 2025). "Conversely, CAFs are positively correlated with the cumulative density of regulatory T cells (Tregs) (Foxp3+), M2 tumor‐associated macrophages (TAMs) (CD163+), and potential Treg‐inducing immune cells (CD80+)." (PMID 39928309, 2025). "CTLA-4 inhibitors exert anti-tumor effects by preventing Tregs from down-regulating CD80/86 expression and depleting Tregs through antibody-dependent cell-mediated cytotoxicity (ADCC) and phagocytosis (ADCP)." (PMID 40356928, 2025). "In the model, T cell activation occurs through the binding of TCR/CD3 complex to major histocompatibility complex (MHC) on APCs and tumor cells, accompanied by the physical interaction between CD80/CD86 on APCs and CD28 on T cells." (PMID 40276607, 2025). "We demonstrate a mechanism of macrophage-driven immune suppression in the tumor environment post-RT via CD80 and CD86-mediated expansion of CD4 T cells and Treg." (PMID 41417245, 2025). "Among the tumors injected with IFNβ-LNPs, TAMs displayed lower levels of the immunosuppressive M2 macrophage marker, CD206, along with increases in the anti-tumor M1 macrophage markers, CD80 and CD86." (PMID 40006725, 2025). "Enhanced systemic immunity was evidenced by elevated CD80+CD86+ mature DC populations in tumor-draining lymph nodes and a maximal M1/M2 ratio (41.8% iNOS+CD206− cells) within SINM + US tumors, indicating durable tumor immune microenvironment (TIME) remodeling." (PMID 40892295, 2025). "As expected, LPS/IFN-γ treatment increased HLA-DR+CD80+ (p = 0.040) expression in macrophages (anti-tumor macrophages) and M-CSF induced CD206+CD163+ (p = 0.0082) macrophages (immunosuppressive macrophages)." (PMID 40362334, 2025). "In this context, we propose to investigate the efficacy of anti-CTLA-4 mAbs combined with anti-CD80 mAbs using a murine tumour model." (PMID 40725864, 2025).
tumor (continued). "We demonstrate using ex vivo 3D tumor models and novel in vivo cell tracking models that radiation results in upregulation of the costimulatory molecules CD80 and CD86 on tumor macrophages and on monocytes that enter the tumor following radiation." (PMID 41417245, 2025). "SRGN and CD206 were upregulated, whereas CD80 was downregulated in subcutaneous tumor tissues in HepG2SG xenograft mice compared with HepG2-NC mice (*p < 0.05, **p < 0.01)." (PMID 41476965, 2025). "As a result, blocking PD-1 and CD80 on aT-sEVs nearly abrogated their function in regulating tumour cell membrane PD-L1, MHC-I and ICAM-1." (PMID 38719909, 2024). "CD80 is expressed on the surface of tumor cells, and it can be used as a molecular target in the process of T-cell anti-tumor immune response." (PMID 39575257, 2024). "Enhanced CD80 expression was observed in tumor cells, which further stimulated the value of T cells, especially CD8+ T cells, in the CD45+ population and elevated PD-L1 expression." (PMID 39263534, 2024). "The expression of the immune checkpoint molecules CD86 and PD-L1 and particularly the reduced expression of CD80 in groups 3 and 4 indicate an influence of the investigated immune checkpoints on tumor regression." (PMID 38962703, 2024). "The levels of sEV PD-1/CD80 in T cells and tumour CAL27 cells were analysed by a nanoparticle flow cytometer and standardised by the QuantumTM MESF (Molecules of Equivalent Soluble Fluorochrome) microsphere kit as previously reported." (PMID 38719909, 2024). "Our results revealed that 40% and 100% irradiated tumor cells increased the proportion of CD80+ CD86+ DCs compared to the control." (PMID 39736508, 2024). "For example, the high expression of CD80 on the cell surface of tumor cells significantly improved the overall survival of patients, while in other tumor cells, CD80 overexpression was an indicator of poor prognosis." (PMID 39575257, 2024). "Here we demonstrate that PD-1 and CD80 carried on immunocyte-derived sEVs (I-sEV) induce an adaptive redistribution of PD-L1 in tumour cells." (PMID 38719909, 2024). "The cluster of differentiation 80 (CD80), also known as B7-1, is a cell surface protein expressed on tumor cells or APCs." (PMID 38590525, 2024). "The development of new strategies for tumor immunotherapy targeting CD80 has good application prospects." (PMID 39575257, 2024). "The ASPIRE system codelivered CD80/86 with an anti-PD-1 antibody, achieving effective reversal of tumour immune suppression and promoting functional remodelling of exhausted T cells in Lewis lung carcinoma (LLC) models and MC-38 colon carcinoma models." (PMID 38302430, 2024). "VSV-p15 enhanced infiltration of DCs compared to other treatments, but both VSV-p14 and VSV-p15 significantly increased CD80 expression on tumor infiltrating DCs, demonstrating an increase in DC activation." (PMID 38750591, 2024). "CD80 has been expressed in different immune cells in a tumor type context dependent, mainly in cells with antigen presenting functions." (PMID 38710724, 2024). "IL-18 signaling promotes the activation and expansion of NK cells and improves their cytotoxicity and tumor activity, as well as the CD80, CD86, and HLA-DR expression in APCs." (PMID 39599846, 2024). "PD-1 inhibitor blocks both PD-L1 and PD-L2, whereas PD-L1 inhibitor also blocks the binding to CD80 which releases CTLA-4-mediated anti-tumor immunity." (PMID 38384808, 2024). "CD40, which is expressed by both tumor cells and macrophages can cause the release of proinflammatory cytokines as well as CD80 and CD86 thereby resulting in augmentation of ant-tumor functions." (PMID 39003350, 2024). "In other studies, it has also been reported that PD-L1 on T cells interacts in trans with CD80 on APCs, and blocking this trans interaction enhances anti-tumor immunity." (PMID 39575257, 2024).
tumor (continued). "Consistent with this, combination treatment of NKT cell immunotherapy with VSV-p14 or VSV-p15 increased the number of splenic and tumor infiltrating CD80+ DCs in both our primary and metastatic models." (PMID 38750591, 2024). "To delve deeper into the effect of TLR5 agonist treatment on macrophage function, particularly the activation of T cell immune responses, we examined the co-stimulatory molecules CD40 and CD80 on macrophages from the tumor and spleen." (PMID 38630304, 2024). "In the mouse tumor model, the levels of the macrophage co-stimulators CD80 and CD86 were higher in tumors of the combination group than in the Mn2+ and IL-12 alone groups." (PMID 38175694, 2024). "The increase in CD11b+CD80+ cell population, representing M1 macrophages, provides a beneficial tumor microenvironment to suppress tumor growth." (PMID 38932378, 2024). "RP tumour-infiltrating myeloid cells expressed high levels of molecules associated with immunosuppression (CD58, CD80, CD163), as well as monocyte activation and dendritic cell maturation (CD40)." (PMID 37758326, 2024). "DCs are highly efficient APCs that activate antitumor CD8+ T cells by phagocytosing dying tumor cells and presenting co-stimulatory molecules, such as CD80 and CD86." (PMID 38994018, 2024). "In general, surface markers such as CD68 and CD80 show anti-tumor effects, while CD163 and CD204 show tumor-promoting effects." (PMID 39199574, 2024). "At the same time, the reduction in tumor Treg prevents the downregulation of costimulatory B7-family proteins (CD80 and CD86) on cDC in a CTLA-4-dependent manner." (PMID 39470607, 2024). "At the endpoint, 25 days post-tumor implantation, we assessed the infiltration of M1 (F4/80+, Cd80+) and M2 macrophages (F4/80+, Cd206+), plotted as a percentage of total live cells." (PMID 39272209, 2024). "Our retrospective clinical study investigated the association between CD80, CD86, and PD-L1 expression, tumor characteristics, prognostic factors, and survival in cutaneous malignant melanoma." (PMID 37614091, 2024). "CTLA-4 is upregulated in tumor-specific T cells and acts as an “off” switch when it binds CD80 (B7-1) or CD86 (B7-2) on the surface of cancer cells." (PMID 38893211, 2024). "We progressively detected the surface marker CD80 associated with M1 macrophages and CD163 associated with M2 macrophages to clarify the proportions of tumor macrophage subtypes." (PMID 38473271, 2024). "In a similar fashion to ovarian cancer, the expression of costimulatory molecules CD80 and CD86 as well as IL12 is upregulated by tumor‐associated DCs and macrophages." (PMID 38109851, 2024). "The results showed that the tail-vein injection of aT-sEVs almost doubled tumour growth and shortened the lifespan of mice in vivo, which was rescued by preblocking PD-1/CD80 on aT-sEVs." (PMID 38719909, 2024). "The density of CD80 immunolabeled tumor cells showed a significant decline from group 1 to groups 3 and 4 (e.g., 5161.6 positive tumor cells per mm2 in group 1 and 1941.12 positive tumor cells per mm2 in group 4; p < 0.05)." (PMID 38962703, 2024). "We observed an increase in F4/80+CD80+ macrophages in the tumor and spleen from the TLR5 agonist monotherapy and combination therapy groups." (PMID 38630304, 2024). "To characterize the cytolytic effect of the CAR/CCR T cell construct on CD19-expressing tumor cells with different expression levels of both CD80 and CD86 we prepared a range of in vitro co-culture experiments." (PMID 38340727, 2024). "Conversely, the combined therapy caused a statistically significant increase in the number of CD8+ T cells and CD80+ M1-like macrophages and a reduction of FoxP3+ Treg in the tumor area compared to the control group." (PMID 38824552, 2024). "These compounds impaired the CTLA-4/CD80 interaction and inhibited tumor growth in syngeneic and hCTLA-4 mice." (PMID 38312352, 2024).
tumor (continued). "For example, in the case of CD80 fusion protein, we can change its affinity, concentration, half-life, and so on, so as to make it more effective, gentle, and sustained in killing tumor cells while reducing the side effects." (PMID 39575257, 2024). "In this regard, it was previously shown that TGF-β-responsive tumor-initiating cells become resistant to adoptive cytotoxic T cell transfer (ACT) immunotherapy by inducing the expression of CD80 in a mouse cSCC model." (PMID 38914547, 2024). "On the other hand, the interaction between CD80 and PD-L1 interferes with the binding of PD-L1 on tumor cells to the inhibitory receptor PD-1 on T cells, thereby promoting T cell immune response." (PMID 39575257, 2024). "By investigating LR interactions involving immunomodulatory targets (CRI-iAtlas), we identified interactions between CD274 (PD-L1), its receptor PDCD1 (PD-1) and its costimulator CD80 (B7-1) exclusively in RP-like tumours." (PMID 37758326, 2024). "In the TC-1 tumor model, the frequency of cDC1s and cDC2s coexpressing CD80 and PD-L1 was significantly increased when RT was combined with CD86 blockade." (PMID 38349740, 2024). "When CTLA4-mediated interactions with squamous cell carcinoma cells were blocked in vitro, tumor-CD80 engaged instead with CD28 on activated T cells." (PMID 39575257, 2024). "DIABLO (permutation test, p < 0.005) identified 15 transcripts in the CD20+ tumor cells (AOIs) to be positively associated with T-cell-rich MCLs, including IL7R, CD47, CD80, CD84 and NLRC5." (PMID 39001353, 2024). "Some researchers have constructed mouse monoclonal antibodies against human CD80 and studied their effects on tumor growth and migration." (PMID 39575257, 2024). "The expression of CD80 on the surface of a variety of tumor cells makes it an alternative target for tumors." (PMID 39575257, 2024). "A stage-specific increase of CD80 expressing cells was recorded in CCH from the tumor bottom to the top, while CD86 was continuously and homogenously expressed at high levels." (PMID 39619201, 2024). "In summary, we discovered that the ligation of PD-L1 on tumour cells by circulating PD-1/CD80+ I-sEVs resulted in an intense and adaptive immunologically ‘cold’ tumour phenotype." (PMID 38719909, 2024). "Co-culture with 3A1-transfected tumor cells also showed some increase in expression of CD80 and CD86." (PMID 39007281, 2024). "The results indicated a positive correlation between the expression of CD80 and the degree of tumor malignancy." (PMID 39575257, 2024). "The expression of CD80 on the tumor surface and its important role in T cell activation also make it a good choice for tumor vaccine adjuvant." (PMID 39575257, 2024). "PD-L1 is a key player in tumor immune suppression, and studies have shown that PD-L1 signaling including PD-1/PD-L1 and CD80/PD-L1 is crucial for T cell migration, modulating transendothelial movements of Tregs and CD4 effector T cells." (PMID 38529320, 2024). "Immune analyses at the endpoint showed that ZCVCT26@D‐Gel, with its capability to induce pseudo‐oncolysis in tumor cells upon bioorthogonal anchoring, resulted in higher frequencies of CD80+CD86+CD11c+ mature DCs in tumor‐draining lymph nodes (TDLNs)." (PMID 38279587, 2024). "Upon establishing the binding specificity of AYA22T-R2-13 to CTLA-4 on cytotoxic T lymphocytes (CTLs), our investigation aimed to uncover its potential in enhancing CTL-mediated tumor cell lysis by disrupting CTLA-4 interactions with the CD80 or CD86 axis." (PMID 38473398, 2024). "Recent studies have shown that the interaction between CD80 and PD-L1 interferes with the binding of PD-L1 of tumor cells to the inhibitory receptor PD-1 on T cells, thereby promoting the immune response of T cells." (PMID 39575257, 2024). "Our current data strongly support the notion that chronic HS diets cause the activation of TISCs, leading to tumorigenesis along with CD80-mediated escape of anti-tumor immune responses." (PMID 38891044, 2024).